ARHGAP22 (Rho GTPase activating protein 22)
Description:
Rho GTPase-activating protein involved in the signal transduction pathway that regulates endothelial cell capillary tube formation during angiogenesis. Acts as a GTPase activator for the RAC1 by converting it to an inactive GDP-bound state. Inhibits RAC1-dependent lamellipodia formation. May also play a role in transcription regulation via its interaction with VEZF1, by regulating activity of the endothelin-1 (EDN1) promoter (By similarity).
Synonyms: RHOGAP2; RhoGap22
Tractability: Antibody: the Human Protein Atlas places it where antibodies can reach. PROTAC: ubiquitination databases record sites on it.
Gene: Protein-coding gene on chromosome 10 (48,446,036 to 48,656,265, reverse strand). Ensembl gene ENSG00000128805.
Subcellular location: Cytoplasm; Nucleus
Subcellular location (Human Protein Atlas): Cytosol; Nucleoplasm; Plasma membrane
Pathways (Reactome):
Signal Transduction: CDC42 GTPase cycle; RAC1 GTPase cycle; RHOA GTPase cycle
Gene Ontology:
Molecular function: protein binding; GTPase activator activity
Biological process: regulation of postsynapse organization; negative regulation of small GTPase mediated signal transduction; regulation of small GTPase mediated signal transduction; signal transduction
Cellular component: cytosol; focal adhesion; glutamatergic synapse; nucleoplasm; plasma membrane; cytoplasm; nucleus
Genetic constraint (gnomAD): Loss-of-function variants: 50 observed, 55.46 expected, observed/expected ratio (o/e) 0.9, 90% interval 0.72 to 1.14. The upper end of that interval is the gene's LOEUF score, 1.14, which puts it in group 5 of 6, group 1 being the genes least tolerant of losing a copy. Missense variants: 1,015 observed, 902.8 expected, observed/expected ratio (o/e) 1.12, 90% interval 1.07 to 1.18. Synonymous variants: 445 observed, 393.61 expected, observed/expected ratio (o/e) 1.13, 90% interval 1.04 to 1.22.
Homologues: Orthologues: chimpanzee ARHGAP22 (99% identical), macaque ARHGAP22 (96% identical), pig ARHGAP22 (87% identical), rat Arhgap22 (83% identical), mouse Arhgap22 (83% identical), guinea pig ARHGAP22 (79% identical), rabbit ARHGAP22 (79% identical), dog ARHGAP22 (71% identical), zebrafish arhgap22b (56% identical), tropical clawed frog arhgap22 (45% identical), zebrafish arhgap22a (29% identical). Paralogues in human: ARHGAP24 (47% identical), ARHGAP25 (39% identical).
Diseases named in the same sentence as ARHGAP22 in open-access papers:
ARHGAP22 is named in the same sentence as 16 diseases in open-access papers, as found by Europe PMC text mining. Sharing a sentence is not in itself a finding about the gene and the disease. The quoted sentences say what the papers report.
melanoma (4 papers, 2014 to 2024). A malignant, usually aggressive tumor composed of atypical, neoplastic melanocytes. "A7 melanoma cells transfected with ARHGAP22 were stimulated with EGF (50 nM) for 30 min and lamellae formation was analyzed by F-actin staining." (PMID 24933155, 2014). "Rac1 activation through ROCK inhibition in MCF-7 cells was expected, as ROCK antagonizes RhoA-dependent Rac1 activation in fibroblasts, and Rac inactivation through ROCK is occurs via FilGAP phosphorylation or ARHGAP22 activation in melanoma cells." (PMID 24523903, 2014). "Recently, ARHGAP22 has been identified as a key mediator that suppresses Rac1 downstream of RhoA and involved in the amoeboid movement of melanoma cells in 3D environment." (PMID 24933155, 2014). "Depletion of endogenous ARHGAP22 by RNAi increased GTP-bound Rac and increased the number of mesenchymal melanoma cells." (PMID 24933155, 2014).
diabetic retinopathy (2 papers, 2018 to 2019). "Variants within ARHGAP22 have been associated with diabetic retinopathy, conduct disorder, daytime sleep, and self-employment, but these associations have not been replicated." (PMID 31134134, 2019).
leukemia (2 papers, 2021 to 2026). A malignant (clonal) hematologic disorder, involving hematopoietic stem cells and characterized by the presence of primitive or atypical myeloid or lymphoid cells in the bone marrow and the blood. "HOPX, DOCK1, DNMT3B, MMRN1, and ARHGAP22 genes were reported as important leukemia stem cell markers." (PMID 33225420, 2021).
type 2 diabetes (2 papers, 2018 to 2025). "The rs3844492/ARHGAP22 and rs741301/ELMO1polymorphisms are associated with alterations in renal function markersamong patients with type 2 diabetes mellitus." (PMID 40271977, 2025). "The aim of this study was to elucidate the relationship between ARHGAP22 expression and EPC levels in type 2 diabetes (T2D) patients with DR." (PMID 29707151, 2018).
breast carcinoma (1 paper, 2022). "Positive responding breast cancer cells upregulated ARHGAP22 by log2 fold change of 1.9, suggestive of Rac1 negative regulation." (PMID 35520391, 2022).
Hypertension (1 paper, 2019). The presence of chronic increased pressure in the systemic arterial system. "Intronic ARHGAP22 rs4593967 was significantly associated with SBP and has not been previously reported as associated with blood pressure or hypertension." (PMID 31134134, 2019).
nicotine dependence (1 paper, 2022). Physical and psychological dependence on nicotine. "For cannabis use disorder, 2 genes were significantly associated including, PDE4B (P = 2.09 × 10−6) and FOXP2 (P = 9.30 × 10−7), and one gene for nicotine dependence—ARHGAP22 (P = 2.42 × 10−6)." (PMID 36151087, 2022).
prostate carcinoma (1 paper, 2024). A carcinoma that arises from epithelial cells of the prostate gland. "What’s more, our research demonstrated that specific genes, encompassing RNASEK, CPEB2, ARHGAP22, and BRD1, were enriched in the different cell clusters of prostate cancer tissues through the single-cell RNA sequencing localization analysis." (PMID 39600951, 2024).
tumor (5 papers, 2014 to 2025). "Recently, ARHGAP22 levels have been proposed to determine tumor cell movement and the ARHGAP22 gene has been implicated in a novel insulin-regulated pathway." (PMID 27863428, 2016). "ARHGAP22 is a member of FilGAP family, and implicated in the regulation of tumor cell motility." (PMID 24933155, 2014). "Recent studies also found that the abrogation of ARHGAP22 promotes tumor cell motility." (PMID 33994864, 2021). "It will be interesting to examine the roles of ARHGAP22 and ARHGAP25 in invadopodia formation of tumor cells." (PMID 37482421, 2023).
cancer (4 papers, 2018 to 2021). A tumor composed of atypical neoplastic, often pleomorphic cells that invade other tissues. "Previous reports have linked ARHGAP22 activity to cell movement and morphology as well as to actin dynamics in cancer, through its RAC1 regulating activity." (PMID 34455539, 2021). "Rho GTPase-activating protein encoded by the ARHGAP22 gene is known to be involved in insulin response mechanisms regulating endothelial cell migration and cancer metastasis." (PMID 30266984, 2018). "In this context, ARHGAP22 protein has been previously shown to specifically inhibit RAC1 activity thus standing as critical cytoskeleton regulator in cancer cell models; however, whether this function is maintained in neurons in the CNS is unknown." (PMID 34455539, 2021). "ARHGAP22 is activated by Rho-kinase signaling and is responsible for cancer cell movement." (PMID 29796168, 2018). "Taken together, these results strongly supported the excellent anti-cancer effects of BRD4 inhibition by JQ1 in sunitinib-resistant ccRCC and suggested that SCG5, SPOCD1, RGS19, and ARHGAP22 may be novel direct targets of the epigenetic reader BRD4 in sunitinib-resistant ccRCC." (PMID 29796168, 2018).
ARHGAP22 also shares sentences with these, for which no sentence is quoted: Anxiety (1 paper); conduct disorder (1); diabetic kidney disease (1); fragile X syndrome (1); memory (1); type 2 diabetes mellitus (1).